CDX4 (caudal type homeobox 4)
Tractability: No criterion of Open Targets' tractability assessment is met for any kind of drug.
Gene: Protein-coding gene on chromosome X (73,447,053 to 73,455,171, forward strand). Ensembl gene ENSG00000131264.
Subcellular location: Nucleus
Subcellular location (Human Protein Atlas): Nuclear speckles; Nucleoplasm; Cytosol
Gene Ontology:
Molecular function: DNA-binding transcription activator activity, RNA polymerase II-specific; protein binding; RNA polymerase II cis-regulatory region sequence-specific DNA binding; sequence-specific double-stranded DNA binding; DNA-binding transcription factor activity; DNA-binding transcription factor activity, RNA polymerase II-specific; RNA polymerase II transcription regulatory region sequence-specific DNA binding; DNA binding
Biological process: positive regulation of transcription by RNA polymerase II; anterior/posterior axis specification; cell differentiation; digestive tract development; embryonic pattern specification; regulation of transcription by RNA polymerase II; regulation of DNA-templated transcription
Cellular component: chromatin; nucleus
Homologues: Orthologues: chimpanzee CDX4 (98% identical), macaque CDX4 (94% identical), pig CDX4 (86% identical), rabbit CDX4 (84% identical), rat Cdx4 (84% identical), mouse Cdx4 (82% identical), dog CDX4 (80% identical). Paralogues in human: CDX2 (39% identical), CDX1 (38% identical).
Diseases named in the same sentence as CDX4 in open-access papers:
CDX4 is named in the same sentence as 11 diseases in open-access papers, as found by Europe PMC text mining. Sharing a sentence is not in itself a finding about the gene and the disease. The quoted sentences say what the papers report.
leukemia (2 papers, 2006 to 2014). A malignant (clonal) hematologic disorder, involving hematopoietic stem cells and characterized by the presence of primitive or atypical myeloid or lymphoid cells in the bone marrow and the blood. "Our results identify a mechanism for increased and sustained CDX4 transcription in leukemias co-overexpressing HoxA9 and HoxA10 in combination with constitutive activation of Shp2." (PMID 25531430, 2014). "Taken together, our studies suggest a coordinated role for Cdx4 and the menin-MLL complex in modulating Hoxa9 expression during MLL-associated myeloid transformations, while Cdx4 is no longer required in full-blown leukemia cells such as AR1 cells." (PMID 17183676, 2006).
acute lymphoblastic leukemia (1 paper, 2022). Leukemia with an acute onset, characterized by the presence of lymphoblasts in the bone marrow and the peripheral blood. "Caudal Type Homeobox 4 (CDX4), a member of the small subfamily of homeobox-containing transcription factors, affects adult acute lymphoblastic leukemia by regulating HOX gene expression." (PMID 36713456, 2022).
acute myeloid leukemia (1 paper, 2016). Acute myeloid leukemia (AML) is a group of neoplasms arising from precursor cells committed to the myeloid cell-line differentiation. "A poor prognosis subtype of acute myeloid leukemia (AML) is characterized by increased expression of a set of homeodomain (HD) transcription factors, including HoxA9, HoxA10 and Cdx4." (PMID 27340869, 2016).
chronic myeloid leukemia (1 paper, 2014). "We found that Cdx4 mRNA expression was significantly greater in AML bone marrow cells relative to bone marrow from either chronic myeloid leukemia or control subjects (P<0.01 by three-way analysis of variance)." (PMID 25531430, 2014).
embryonal carcinoma (1 paper, 2022). A non-seminomatous malignant germ cell tumor characterized by the presence of large germ cells with abundant cytoplasm resembling epithelial cells, geographic necrosis, high mitotic activity, and pseudoglandular and pseudopapillary structures formation. "Among expression-related genes, CDX4 and FOXD3 were significantly overexpressed in embryonal carcinoma, whereas CUX2 and RPS6KA5 were increased in seminoma." (PMID 36713456, 2022). "Our analysis suggested that the expression of CDX4 and FOXD3 from TGCT cohort was significantly higher in embryonal carcinoma than in seminoma, which was verified by qRT-PCR experiments." (PMID 36713456, 2022).
spina bifida (1 paper, 2023). A congenital neural tube defect in which vertebrae are not fully formed. "In particular, the closed form of spina bifida was partly due to reduced Pax3 and Cdx4 gene expression in the posterior dorsal neural tubes of Gpr161 mutant embryos with decreased Wnt signaling, whereas Shh signaling was increased." (PMID 37885410, 2023).
tumor (2 papers, 2023). "Studies to further clarify whether MED12 interacts with CDX4 or HOX genes at chromatin levels and whether the interaction is altered by mut-MED12 will be important in increasing our understanding of mut-MED12–linked tumor growth, which is beyond the scope of the current study." (PMID 37607000, 2023).
CDX4 also shares sentences with these, for which no sentence is quoted: anemia (1 paper); insulinoma (1); seminoma (1); Splenomegaly (1).